SHE (Src homology 2 domain containing E)
Tractability: PROTAC: ubiquitination databases record sites on it.
Gene: Protein-coding gene on chromosome 1 (154,469,772 to 154,502,472, reverse strand). Ensembl gene ENSG00000169291.
Subcellular location (Human Protein Atlas): Nucleoplasm; Cytosol
Gene Ontology:
Molecular function: protein binding; phosphotyrosine residue binding
Genetic constraint (gnomAD): Loss-of-function variants: 11 observed, 46.35 expected, observed/expected ratio (o/e) 0.24, 90% interval 0.15 to 0.39. The upper end of that interval is the gene's LOEUF score, 0.39, which puts it in group 1 of 6, group 1 being the genes least tolerant of losing a copy. Missense variants: 624 observed, 640.78 expected, observed/expected ratio (o/e) 0.97, 90% interval 0.91 to 1.04. Synonymous variants: 310 observed, 262.68 expected, observed/expected ratio (o/e) 1.18, 90% interval 1.08 to 1.3.
Homologues: Orthologues: chimpanzee SHE (99% identical), macaque SHE (98% identical), pig SHE (93% identical), rabbit SHE (86% identical), mouse She (83% identical), rat She (83% identical), guinea pig SHE (80% identical), dog SHE (77% identical), tropical clawed frog she (54% identical), zebrafish she (45% identical). Paralogues in human: SHF (34% identical), SHB (32% identical), SHD (27% identical).
Diseases named in the same sentence as SHE in open-access papers:
SHE is named in the same sentence as 13 diseases in open-access papers, as found by Europe PMC text mining. Sharing a sentence is not in itself a finding about the gene and the disease. The quoted sentences say what the papers report.
breast carcinoma (1 paper, 2025). "The down-expression of TMEM220 and SHE genes (also in connection with hyper-methylation) has been repeatedly indicated as a significant factor important in the formation and development of cancer but not necessarily breast cancer (Refs." (PMID 40724805, 2025).
cervical cancer (1 paper, 2017). A primary or metastatic malignant neoplasm involving the cervix. "Moreover, hypermethylation of LYPD2 and SHE were associated with poor overall survival (OS); hypermethylation of FGF8 and HSPA6 were associated with poor progression free survival (PFS) in patients with cervical cancer." (PMID 29029430, 2017).
non-alcoholic fatty liver disease (1 paper, 2025). "sHE catalyzes the conversion of EETs to DHETs, making sEH inhibitors potential treatments for non-alcoholic fatty liver disease (NAFLD) by decreasing lipid peroxidation, inflammation, and fibrosis." (PMID 40626231, 2025).
cancer (3 papers, 2017 to 2025). A tumor composed of atypical neoplastic, often pleomorphic cells that invade other tissues. "We analyzed the methylation status of these genes in TCGA database and found the methylation of SHE, HSPA6 and FGF8 were lower in normal tissue then cancer tissue." (PMID 29029430, 2017).
SHE also shares sentences with these, for which no sentence is quoted: tumor (2 papers); bladder cancer (1); chronic myeloid leukemia (1); gallbladder cancer (1); gastric cancer (1); Hyperkeratosis (1); melanoma (1); pancreatic cancer (1); sarcoma (1).